CD86 (CD86 molecule)
Diseases named in the same sentence as CD86 in open-access papers (continued):
Sharing a sentence is not in itself a finding about the gene and the disease.
tumor (continued). "Accordingly, the similar levels of M1 macrophage marker CD86 were observed in the tumor microenvironment of PKTP and PKP PDAC." (PMID 31109321, 2019). "A significantly increased number of CD3+ and CD86+ positive cells were seen in the secondary tumor of the H-RT+L-TBI group compared to the other groups." (PMID 30873170, 2019). "Since irradiation triggers an immune response, we also assessed the infiltration of CD3+ and CD86+ lymphocytes in the primary and secondary tumor tissue." (PMID 30873170, 2019). "This first encounter and its consequences profoundly shapes the immune infiltrate, enhancing the frequency of CD86+ cells among both cDC1 and cDC2 within the tumor." (PMID 30949170, 2019). "In the secondary tumor, the number of CD86+DC cells was significantly increased after combination therapy." (PMID 30873170, 2019). "Specifically, cytotoxic lymphocyte-associated protein 4 (CTLA-4) is a co-inhibitory receptor which, through binding to CD80 (B7.1) and CD86 (B7.2) ligands expressed on tumor cells and APCs, inhibits the process of T cell priming and activation." (PMID 31788395, 2019). "After exposure to the combination of chemotherapy and immunotherapy, more dendritic cells were present in the tumor microenvironment, which were highly activated by chemotherapy as indicated by the elevated expression of costimulatory molecules CD86 and CD80." (PMID 31362778, 2019). "Increased priming was also supported by our observation of increased T cell frequency and increased expression of costimulatory molecules CD40 and CD86 on APCs in the tumor-draining lymph nodes." (PMID 31921384, 2019). "Meanwhile, macrophages co-cultured with eosinophils from tumour-bearing mice or cryo-thermal treated mice both resulted in a decrease of M1 macrophage (CD11b+F4/80+CD86+MHCII+) population as compared to tumour-bearing macrophages alone." (PMID 31519961, 2019). "It is believed that CTLA-4 impacts on the stage of T-cell activation mainly in the draining lymph nodes by removing CD80/CD86 from the surface of antigen-presenting cells, thus decreasing the ability to effectively stimulate tumor-specific T cells." (PMID 31581738, 2019). "CTLA-4 can trigger apoptosis in CTLA-4-expressing tumour cells after the cells interact with soluble CD80 or CD86 recombinant ligands, and the induction of apoptosis occurs through a caspase-8-dependent mechanism." (PMID 31506501, 2019). "Despite the reduced total number of cDCs (CD11b+ and CD103+) found in tumor infiltrates from poly A:U-treated animals, greater proportions of them were activated as judged by CD86 expression level." (PMID 30949170, 2019). "Consistent with this notion, we showed that intra-tumoral CD103+ DCs, known to play a role in cross-presentation of tumor antigen, expressed increased levels of the dendritic cell activation marker and T cell co-stimulatory ligand CD86." (PMID 31036082, 2019). "Second, Tα1 fused with the Fc domain of human IgG4 plays anti-tumor effects in the 4T1 and B16.F10 tumor xenograft models by upregulating CD86 expression, secreting IFNγ and IL-2, and increasing the number of tumor-infiltrating CD4+ and CD8+ T cells." (PMID 31555601, 2019). "On the other hand, a decline was noted in the proportions of CD68+MHCII+F4/80+ M1 and CD68+MHCII+CD86+CD206+ M2 macrophages in the tumor-infiltrate and spleen of Dll1-ablated mice." (PMID 30940183, 2019). "Specifically, eCPMV treated mice showed significantly elevated levels of leukocytes (CD45+ cells), CD11b+CD11c+ DCs, CD11bint-lowNK1.1+ NK cells, CD11b+Ly6G− monocytes, and CD11b+Ly6G+MHCII+CD86+ TINs compared with PBS-treated tumor bearing mice." (PMID 30974896, 2019). "Accordingly, we found that CPMV increased the population of activated dendritic cells (CD11c/CD86+) in the primary tumor." (PMID 31453050, 2019).
tumor (continued). "In contrast, the combination of Y27632 and Dox increased CD40 and CD86 expression as well as cross-presentation of OVA-derived peptide to MHC-I in DCs from tumour-draining LNs of B16F10-Ova tumour-bearing mice." (PMID 29867097, 2018). "The level of matured dendritic cells (CD80+/CD86+ cells) in the tumor draining lymph node of PSPEI-PAA treated tumor mice were enhanced and therefore CD8+ T cells infiltration in the tumor were enriched." (PMID 30960988, 2018). "Ectopic expression of these molecules and their ligands (CD80, CD86, and PD-L1) downregulates the activities of antigen-presenting cells and tumor-specific T cells through direct cell-to-cell interactions with Tregs." (PMID 30619286, 2018). "Research has shown that HDACis can upregulate the expression of CD80 and CD86, hence improving tumor cell immunogenicity, promoting the elimination of tumor cells, and enhancing the treatment efficacy of antibodies targeting CTLA-4." (PMID 30558227, 2018). "In 4T1 tumor models, mice treated with Tα1-Fc, compared with Tα1, showed an increased expression of CD86 and promoted CD4+ T lymphocytes and CD8+ T lymphocytes infiltrating tumor tissues." (PMID 30120362, 2018). "CTLA-4 is structurally similar to CD28 and binds to CD80 (B7-1) / CD86 (B7-2) on APCs (or tumor cells) at a higher affinity than CD28, which suggests an interference with T cell activation." (PMID 29988281, 2018). "The HSPC-derived cells are extremely effective due to the high expression of co-stimulatory markers like CD86, which facilitates potent anti-tumor immunity." (PMID 30619286, 2018). "The dysregulation of PD-1 ligands (PD-L1 and PD-L2) and CTLA-4 ligands (CD80 and CD86) represents a tumor strategy to escape the immune surveillance." (PMID 30123257, 2018). "Dendritic cells ingesting tumor ACs which activated T cells showed upregulation of the costimulatory ligand CD86 secondary to AC phagocytosis." (PMID 30002409, 2018). "Like CD28, CTLA4 is able to bind to CD80 and CD86, which are expressed on the surface of tumor cells and APCs." (PMID 30558227, 2018). "There were significantly more iNOS+/CD86+ cells in high PKN2 expression tumor tissues, while the number of CD206+/CD163+ cells was significantly higher in low PKN2 expression tumor tissues." (PMID 29368606, 2018). "In our study incubation of DC with tumor supernatant significantly lowered the expression of CD83, CD86 and HLA-DR, confirming the immunosuppressive effects of the tumor." (PMID 28719632, 2017). "DCs that migrated toward SN of CT26 cells particularly upregulated the activation markers CD80 and CD86 when in contact with SN of irradiated tumor cells." (PMID 28337197, 2017). "The percentages of MHC-II and CD86 in tumor-bearing mice were significantly decreased at 1, 3, 5 and 7 weeks after LLC inoculation compared with Control, whereas the percentage of CD80 was not statistically different." (PMID 29383114, 2017). "HIFU-stimulated IFN-gamma and TNFα induction and increased CD86 expression in tumor tissue; this was mediated by miR-134 whose direct targets include CD86." (PMID 29112174, 2017). "Due to increased expression of CD86 on surface of the MC38/shTGFβ1-1 tumor-infiltrating PMN-MDSC and M-MDSC, the suppressor activity of splenic myeloid CD11b+ cells was also evaluated." (PMID 28713366, 2017). "Although T cells expanded by the co-electroporation of OKT3-28BB with CD86 and 4-1BBL showed an increased central memory phenotype, the T cells still maintained tumor lytic activities as potent as those of OKT3/IL-2 or OKT3-28BB-stimulated T cells." (PMID 28523432, 2017). "Consistently, inhibition of LSD1 in vivo significantly blocks tumor growth and induces a prominent increase of CD11b and CD86." (PMID 29156705, 2017). "Inhibitory effects of CO on tumor growth were blocked with anti-CD86 neutralizing antibody, suggesting importance of CD86 positive population in mediating CO effects." (PMID 26993595, 2016).
tumor (continued). "To functionally test the role of CD86-positive myeloid cells in the tumor microenvironment in anti-tumoral effects of CO treatment, we depleted the CD86-postive population using anti-CD86 neutralizing antibody." (PMID 26993595, 2016). "In our model, DC maturation with up-regulation of CD40, CD80 and CD86 was measured in tumor draining LN after IL PV-10." (PMID 27177220, 2016). "We showed the importance of a CD86-positive population of myeloid cells in controlling CO anti-tumor responses." (PMID 26993595, 2016). "Before loading with tumour lysate, DCs were characterized by flow cytometry to analyse the expression of MHC class I and II molecules, costimulatory molecules (CD86, CD80, CD40), and markers associated with maturation (CD83, CCR7, PD-L1)." (PMID 26795765, 2016). "In our study, we found that MHCII I-A/I-E, CD80, and CD86 were down-regulated in TREM-2+CD11c+DCs from tumor-bearing mice." (PMID 27102437, 2016). "Next, we investigated if HIFU enhanced anti-tumor immunity by inhibiting the negatively regulatory role of miR-134 on CD86 in B16F10 cells." (PMID 26485753, 2015). "All these results support the idea that HIFU enhances anti-tumor immunity through suppressing miR-134 to increase CD86 expression in B16F10 cells that promotes T cell activation." (PMID 26485753, 2015). "Such CD86-expressing irradiated autologous tumor cell vaccines have been evaluated in combination with subcutaneous IL-2 administration in a phase II study involving 66 stage IV renal cell carcinoma patients." (PMID 26343191, 2015). "Second-generation CARs that express CD28-containing costimulation in the CD19+CD80/CD86-ALL SCID-beige tumor model showed superior in vivo tumor activity and T cell function." (PMID 26377367, 2015). "APCs presenting a self-tumor antigen in the presence of a costimulatory signal in the form of upregulated CD80 or CD86 (normally triggered by a microbial stimulus) induce either anergy, deletion of tumor-specific T cells, or expansion of T-regulatory cells." (PMID 26221602, 2015). "Of the remaining antigens, CD86, although apparent on the surface of >85% of cells from all three tumor models, was most reactive (as based upon MESF) on RPCI-WM1 followed by BCWM.1 and least on MWCL-1 cells." (PMID 25853860, 2015). "CD86+ activated B cells were significantly elevated in tumor tissue compared with PBMCs of healthy controls and CRC patients." (PMID 25026291, 2014). "CD80 and CD86 are essential for immune responses to most pathogens as well as for elimination of tumor cells by the immune system." (PMID 25371237, 2014). "Our findings demonstrate that the addition of GK-1 to BMDCs loaded with MAGE-AX decreases the rate of tumor growth and increases the survival of mice and the expression of CD86 and IL-12 in the BMDCs, as well as the levels of CD8 IFNγ producing T cells." (PMID 25759825, 2014). "The percentage of infiltrating CD86+/F4/80+ cells in the GPC3-expressing tumor was approximately 15.93% in the region of monocytes and macrophages, whereas it was only 5% in the control tumors." (PMID 24992906, 2014). "In summary we have observed that treatment with 177Lu-DOTATATE PRRT in our human xenograft tumor model of NET results in increased CD86+ APC infiltration and increased expression of CD86 on these cells." (PMID 26824927, 2013). "We have shown that treatment with 177Lu-DOTATATE leads to both increased tumor infiltration by CD86+ APCs and higher level of CD86 expression on these APCs." (PMID 26824927, 2013). "Since many immunogenic tumors lack expression of CD80 and CD86, it was postulated that tumor-infiltrating T cells would receive chronic TCR stimulation without co-stimulation leading to T cell anergy." (PMID 23450201, 2013). "To assay the effect of 177Lu-DOTATATE treatment on APC tumor infiltration and capacity to present tumor antigens, we used flow cytometry and immunohistochemistry to look for CD86 expressing cells in tumor preparations." (PMID 26824927, 2013).
tumor (continued). "Our findings uncover a novel function of CTLA4Ig in tumor immunity and suggest that CD86 on NK cells is an activating receptor and closely involved in the CTLA4Ig-mediated anti-tumor response." (PMID 24349559, 2013). "The expression of CD86 on NK cells was significantly increased following activation with both YAC-1 tumor cells (from 6.2% to 12.6%) and cytokine IL-15 in vitro." (PMID 24349559, 2013). "While tumours from mice injected SCCVII cells contained DCs expressing either CD80 or CD86 alone, tumours formed by S12.5-injected mice contained DCs that co-expressed these two co-stimulatory molecules." (PMID 24251770, 2013). "In the current model, however, CD86, a M1 macrophage marker, was notdifferent in COX-2MECKO tumor associated F4/80+ cells(macrophages) or in isolated CD45+ TILs, compared to WT." (PMID 24004819, 2013). "By using NCI-H727 cells in an in vivo murine xenograft model of human NETs, we showed that 177Lu-DOTATATE PRRT led to increased infiltration of CD86+ antigen presenting cells into tumor tissue." (PMID 26824927, 2013). "Due to its role in maintaining tolerance, blocking CTLA-4 interaction with CD80 and CD86 was postulated to promote anti-tumor immunity." (PMID 23450201, 2013). "More importantly, we found that these slow-cycling cells expressed a lower level of MHC class I molecules, but a higher level of class II, as well as a higher level of the co-stimulatory molecules CD80 and CD86, compared with conventional tumor cells." (PMID 23270473, 2012). "Tumor cells can escape the immune system by overexpressing molecules of the B7 family, e.g. B7-H1 (PD-L1 or CD86), which suppresses the anti-tumor T-cell responses through binding to the PD-1 receptor, and similarly for B7.1 (CD80), through binding to CTLA-4." (PMID 21884581, 2011). "Pre-treatment of monocyte derived dendritic cells with this tumour conditioned media inhibited the up-regulation of CD86, CD83, CD54 and HLA-DR in response to LPS, enhancing IL-10 while reducing IL-12p70 secretion." (PMID 22125641, 2011). "Tumour cells remained CD86-, MHC class II- and B7-H2-negative after all treatments (data not shown)." (PMID 22015556, 2011). "DCs maturation was evaluated by IL-12/IL-10 production and CD80/CD86 expression after co-culture with tumor cells treated with different HIFU." (PMID 20105334, 2010). "The expression of CD80 and CD86 co-stimulatory molecules were also decreased in the RBP-J-/- DCs compared with the RBP-J+/- DCs after the tumor antigens stimulation." (PMID 20420708, 2010). "Recently, it was proposed that IKDCs found in central lymphoid organs and tumours are the in vivo mouse correlates of human NK cells that display DC-like properties, such as expression of CD86, MHCII and potential to present pre-processed peptides to T cells." (PMID 19784375, 2009). "The immunization of animals with specific tumor cells transduced to express HLA class II and the costimulatory molecules CD80/CD86 have been shown to halt tumor progression and establish an immune memory against the specific tumor." (PMID 20016802, 2009). "DCs found within the tumor microenvironment are found to have a relatively immature phenotype characterized by low levels CD86, and surface HLA-DR expression and inability to produce pro-inflammatory cytokine." (PMID 18533025, 2008). "Upon binding of BIg5 to ErbB2 on tumor cells, these cells display CD86 on their surface and thus can deliver costimulatory signals for T-cell activation." (PMID 15242515, 2004). "Immunofluorescence staining of tumor tissues from nude mouse models treated with Cu-VT NPs revealed a pronounced upregulation of M1 macrophage markers, including CD86 and inducible nitric oxide synthase, alongside a concomitant downregulation of M2 markers such as CD206 and arginase-1." (PMID 41424843, 2026).
tumor (continued). "Notably, the release of DAMPs and cytokines further enhanced the maturation of dendritic cells, as shown by the upregulation of CD80 and CD86 expression on BMDCs exposed to tumor-conditioned media." (PMID 41484455, 2026). "Based on mIHC assay, we revealed abundant CD83+ and CD86+ antigen-presenting cells within peritumoral stroma of pre- and post-treatment samples of responders, indicative of enhanced anti-tumor immunity." (PMID 41355948, 2026). "SLT also plays a crucial role in modulating the tumor immune microenvironment by influencing macrophage polarization: it promotes the shift of M0 macrophages toward the M1 phenotype, marked by increased CD86+ cells, while inhibiting the M2 phenotype, characterized by decreased CD206+ cells." (PMID 40330466, 2025). "Extracellular ATP activates the P2X7 receptor on Mφ surface, inducing NLRP3 inflammasome-dependent IL - 1β release and upregulating the expression of MHC-II molecules and costimulatory molecules CD80/CD86, thereby promoting the cross-presentation of tumor antigens to CD4+ T cells." (PMID 41019083, 2025). "Meanwhile, the M1 marker CD86 maintained a higher level in macrophage from GB2 treated tumor." (PMID 39744236, 2025). "Last, there was an upregulation of surface CD80 and CD86 expression in the Ly6C+MHC-II+ macrophages, suggesting that anti-PDL-L1 therapy attenuated the loss of inflammatory gene expression following tumour infiltration." (PMID 40523200, 2025). "Moreover, addition of Akt inhibitor to RT + αPD-L1/αCTLA-4 therapy further enhanced the anti-tumor efficacy by increasing proportion of M1/M2 ratio and CD86+ DCs in a syngeneic murine TNBC model." (PMID 41378083, 2025). "Moreover, by immunofluorescence, we demonstrated that GA treatment remarkably reduced the M2 CD206+ cell number in the tumor tissues, while the M1 CD86+ cell number increased in the TME." (PMID 40270598, 2025). "Consistently, DS-treated MC38 cells up-regulated the levels of M1-associated costimulatory molecules, including CD86 and MHC-II, while markedly down-regulating CD206, a surface marker of M2 macrophages, indicating that DS-treated tumor cells polarize macrophages." (PMID 40625660, 2025). "In this model, as in ours, positive predictors were tumor microenvironment cells, tumor-associated macrophages (TAMs) and PD-L1 ligands, while increased CD86 expression turned out to be a negative prognostic indicator." (PMID 40426873, 2025). "Moreover, the number of inflammatory immune cells (CD8‐positive T cells, dendritic cells, macrophages, NK cells, and Th1 cells), which can support tumor growth, was higher in the CD86‐high group." (PMID 40635602, 2025). "SU-DHL-1 expressed CD86, at the mRNA level, and CD86 of tumor origin might intervene to alter the thin equilibrium that decides T cell activation threshold." (PMID 41469691, 2025). "A possible link between CD86 and Casp-3 points to a role of CD86 in tumor cell death." (PMID 40271486, 2025). "Taken together, the IF results confirmed that ΔCD24a 4T1 tumors exhibited an immune active phenotype, characterized by more abundant of tumor-suppressive immune cells including CD86+ M1 macrophages and cytotoxic CD8+ T cells compared to the pro-tumor immune suppressive phenotype of the 4T1 tumors." (PMID 40783744, 2025). "Notably, dendritic cell (DC) populations showed a different trend: cDC2s increased after RT, whereas CD86+ DCs were enriched in the immunotherapy group, suggesting distinct effects of these treatments on immune function and tumor control." (PMID 40475579, 2025). "Interestingly, this seemed to be accompanied by an increased activation of DCs across tissues, as identified by the upregulation of the co‐stimulatory molecule CD86 on surface of DCs in the skin drLN, spleen, and tumour." (PMID 39873184, 2025). "In this case, the presence of CD86 facilitated the anti‐tumor effect." (PMID 40635602, 2025).